TH2LCRR (T helper type 2 locus control region associated RNA)
Synonyms: TH2-LCR
Gene: Long non-coding RNA gene on chromosome 5 (132,629,735 to 132,664,272, reverse strand). Ensembl gene ENSG00000223442.
Diseases named in the same sentence as TH2LCRR in open-access papers:
TH2LCRR is named in the same sentence as 4 diseases in open-access papers, as found by Europe PMC text mining. Sharing a sentence is not in itself a finding about the gene and the disease. The quoted sentences say what the papers report.
tumor (1 paper, 2020). "Meanwhile, the other 13 lncRNAs (AC008781.2, HULC, AC100839.1, CRAT37, LINC01198, LINC01482, SMAD1‐AS2, TH2LCRR, DISC1‐IT1, ABCC5‐AS1, NFIA‐AS1, AC007431.1, AC012494.1) were up‐regulated and hypomethylated in CC tumor group which confirmed our previous MethylRad sequencing results." (PMID 32869528, 2020).
TH2LCRR also shares sentences with these, for which no sentence is quoted: allergic disease (1 paper); asthma (1); osteosarcoma (1).